OTUD1 (OTU deubiquitinase 1)
Diseases named in the same sentence as OTUD1 in open-access papers (continued):
Sharing a sentence is not in itself a finding about the gene and the disease.
acute graft versus host disease (2 papers, 2023 to 2024). A syndrome of immunologically mediated tissue damage that may occur following an allogeneic transplant, usually affecting the skin, liver, and GI tract. "Recently, a contribution to the severity of T-cell-mediated acute graft-versus-host disease in mice was shown via the OTUD1-dependant accumulation of Notch2-ICD, inducing a shift towards the pro-inflammatory Th17 phenotype." (PMID 39201568, 2024).
colitis (2 papers, 2022 to 2025). Inflammation of the colon. "In dextran sulfate sodium-induced colitis mice, OTUD1 binds to RIPK1, removing K63-linked polyubiquitination and inhibiting NF-κB activation, reducing pro-inflammatory cytokines and preventing colitis." (PMID 40500776, 2025). "OTUD1 promotes inflammation in myocardial injury by activating NF-κB signaling but paradoxically suppresses colitis by deubiquitinating RIPK115." (PMID 40500776, 2025). "Histologic scores of colitis were significantly higher in the middle and distal colon of DSS-treated Otud1−/−-mice, as compared with DSS-treated Otud1+/+ mice." (PMID 35941131, 2022).
colorectal cancer (2 papers, 2025). A primary or metastatic malignant neoplasm that affects the colon or rectum. "OTU deubiquitinase 1 (OTUD1) has been reported to increase the susceptibility of colorectal cancer (CRC) to ferroptosis, enhancing antitumor immunity through the deubiquitination of IREB2." (PMID 40607253, 2025).
glioma (2 papers, 2022 to 2023). A benign or malignant brain and spinal cord tumor that arises from glial cells (astrocytes, oligodendrocytes, ependymal cells). "Among the selected DUBs significantly linked to the DNA damage repair pathway, the glioma and MB datasets shared several DUBs, including USP1, USP47, UCHL5, and OTUD1, which cover five major DNA damage repair pathways (BER, NER, FA, TLS, DSB)." (PMID 37892185, 2023). "Interestingly, not much is known about the functions of OTUD1, TCHH, ADPRH, PLBD1, and QPCT in glioma, which need further research in future." (PMID 36389681, 2022).
ischemic stroke (2 papers, 2023). A stroke disorder caused by obstruction of blood flow to the brain, due to thrombotic (local blood clot formation) or embolic (due to a blood clot or other material traveling from another site) event. "We also demonstrated that inhibition of RIP2 by GSK559, a small molecule inhibitor, improved the ischemic stroke outcomes, while OTUD1 deficiency exacerbated cerebral ischemic injury." (PMID 38012669, 2023). "This study, through meta-analysis, for the first time reveals the relationship between herpesviruses, the OTUD1/NF-κB signaling pathway, and ischemic stroke." (PMID 37695739, 2023).
myeloma (2 papers, 2022 to 2023). "Because PRDX4 is an important component of the ER folding machinery, we speculated that changes in the amount of iIgL in myeloma cells with altered OTUD1 expression might be caused by variations in the PRDX4 protein quantity." (PMID 36357400, 2022). "Since our data indicate that OTUD1 activity correlates with the amount of iIgL, ubiquitinated products, and MM patient survival, we hypothesized that changes in the iIgL levels and IgL ubiquitination caused by altered OTUD1 expression might result in a different myeloma response to PIs." (PMID 36357400, 2022). "As expected, OTUD1 oe suppressed myeloma cell growth while introduction of sh OTUD1 promoted proliferation." (PMID 36357400, 2022). "Altogether, our results indicate that OTUD1 regulates synthesis of IgL and the vast amount of ubiquitinated proteins in myeloma cells belongs to misfolded Igs that are responsible for clogging proteasome." (PMID 36357400, 2022). "In myeloma cells, OTUD1 negatively affected progression through the cell cycle independently of the Ig expression." (PMID 36357400, 2022). "While exploring the mechanism behind the modulation of iIgL levels by OTUD1, we noticed dramatic changes in total ubiquitin pools in myeloma cells with altered OTUD1 expression." (PMID 36357400, 2022). "Because both our and public data imply a potential inhibitory effect of OTUD1 expression on myeloma aggressiveness, we tested the proliferation capacity of our OTUD1 genetic models." (PMID 36357400, 2022). "Here, the authors show that deubiquitinase OTUD1 protects PRDX4 from degradation resulting in increased load of misfolded immunoglobulins sensitizing myeloma cells for proteasome inhibition." (PMID 36357400, 2022). "We applied this drug panel together with bortezomib to PI-resistant sh OTUD1 (iIgL low) myeloma cells." (PMID 36357400, 2022). "On the other hand, differences in myeloma cell proliferation caused by differential OTUD1 expression were not changed by normalizing PRDX4 protein levels or by restoring the IgL levels." (PMID 36357400, 2022). "Additionally, the concentration of iIgL in myeloma cells extracted from the mouse xenografts correlated with OTUD1 levels." (PMID 36357400, 2022). "Additionally, immunoprecipitation of IgL from myeloma cells with OTUD1 oe revealed an increase in IgL ubiquitination while ubiquitination of IgL dropped in sh OTUD1 cells." (PMID 36357400, 2022). "Analysis of proteasome expression and activity did not reveal any differences in myeloma cells with OTUD1 oe." (PMID 36357400, 2022). "As we observed this phenomenon only in myeloma but no other cell lines, and OTUD1 regulates IgL production in plasma cells, we hypothesized that the differences in global ubiquitination might be caused by alteration in the iIgL levels." (PMID 36357400, 2022). "At the same time, none of the tested phenotypes altered upon OTUD1 expression in myeloma cells (Ig production, proliferation, PI sensitivity) was affected by the absence of the KEAP1-binding site in OTUD1, prompting us to further investigate the role of PRDX4." (PMID 36357400, 2022).
nasopharyngeal carcinoma (2 papers, 2025). A carcinoma arising from the nasopharyngeal epithelium. "In contrast, other OTU members exert anti-cancer effects in specific cancers, such as YOD1 in HNSCC and cervical cancer; OTUD1 and OTUD6B in clear cell renal cell carcinoma (ccRCC); TNFAIP3 in nasopharyngeal carcinoma (NPC)." (PMID 40469292, 2025).
rheumatoid arthritis (2 papers, 2023 to 2024). A chronic, systemic autoimmune disorder characterized by inflammation in the synovial membranes and articular surfaces. "Notably, the OTUD1 mutations P95R, R243C, P379S, T407P, P420L, and G430V were identified in systemic lupus erythematosus (SLE), rheumatoid arthritis (RA), and ulcerative colitis (UC) patients." (PMID 36829909, 2023).
Stroke (2 papers, 2023). Sudden impairment of blood flow to a part of the brain due to occlusion or rupture of an artery to the brain. "Combined with GEO chip differential analysis and WGCNA co-expression analysis, it identified the key gene OTUD1 and its downstream NF-κB signaling pathway associated with latent herpesvirus infection and stroke." (PMID 37695739, 2023). "This study provides a research foundation for developing drugs for the prevention or treatment of stroke and provides important evidence for the important role of the OTUD1/NF-κB signaling pathway in the recovery process of stroke." (PMID 37695739, 2023). "To further explore the mechanism by which OTUD1 regulates stroke in herpes simplex virus latent infection, we performed single-gene correlation analysis on the stroke samples in the GSE22255 dataset and obtained 4848 genes significantly positively or negatively correlated with OTUD1." (PMID 37695739, 2023). "Therefore, we speculate that OTUD1 may mediate the occurrence of stroke in herpes simplex virus latent infection by activating the NF-κB signaling pathway." (PMID 37695739, 2023). "Therefore, we speculate that OTUD1 may be a key gene in the mechanism of herpesvirus latent infection-induced stroke." (PMID 37695739, 2023). "It leads us to speculate that OTUD1 may play a role downstream of various biological processes, and while there is currently no direct evidence linking OTUD1 to stroke, it may have some impact on stroke occurrence through NF-κB." (PMID 37695739, 2023). "Focal cerebral ischemia was introduced by middle cerebral artery occlusion (MCAO) in wild-type (WT) and OTUD1-deficient (OTUD1−/−) mice, oxygen glucose deprivation and reoxygenation (OGD/R) models in BV2 cells and primary cultured astrocytes were performed for monitoring of experimental stroke." (PMID 38012669, 2023). "ROC curve analysis indicated that OTUD1 and NFIL3 could predict stroke occurrence with a certain degree of accuracy, while OSM could not." (PMID 37695739, 2023).
systemic lupus erythematosus (2 papers, 2023 to 2024). An autoimmune multi-organ disease typically associated with vasculopathy and autoantibody production. "OTU Deubiquitinase 1 (OTUD1; C−A+ quadrant) has been shown to repress type-I interferon-mediated disease, which includes lupus, in vivo and to have loss-of-function in systemic lupus erythematosus, suggesting the promise of treatments that increase the activity of OTUD1 in lupus B cells." (PMID 39336806, 2024).
Ataxia (1 paper, 2022). Ataxia refers to impaired coordination of voluntary muscle movement. "OTUD1 encodes a deubiquitinase, and mutations in this gene were reported to be associated with the development of neurological phenotypes including ataxia with cerebellar atrophy and dementia." (PMID 35528544, 2022).
Autoimmunity (1 paper, 2024). The occurrence of an immune reaction against the organism's own cells or tissues. "Since OTUD1 influences cytokine production and has an impact on the evolution and maintenance of experimental autoimmunity, we postulate an MR-mediated contribution to the course of MS." (PMID 39201568, 2024).
breast tumors (1 paper, 2017). "In a large public clinical microarray database of human breast tumors, we found a trend towards good prognosis for OTUD1-high patients." (PMID 29235476, 2017).
cerebral infarction (1 paper, 2023). An ischemic condition of the brain, producing a persistent focal neurological deficit in the area of distribution of the cerebral arteries. "ROC curve analysis identified the key gene OTUD1, and the correlation and pathway enrichment analyses showed that OTUD1 regulates the NF-κB signaling pathway to mediate cerebral infarction." (PMID 37695739, 2023). "We used ROC curve analysis to identify the key gene OTUD1 for predicting the occurrence of cerebral infarction and combined correlation and pathway enrichment analyses to identify the downstream pathways regulated by OTUD1." (PMID 37695739, 2023). "Although there is no literature data to directly link OTUD1 to cerebral infarction, we have identified OTUD1 as a key gene linking herpes virus latent infection and cerebral infarction." (PMID 37695739, 2023).
Cerebral ischemia (1 paper, 2023). Restriction of arterial blood supply to the brain associated with insufficient oxygenation to support the metabolic requirements of the tissue. "Furthermore, we demonstrated OTUD1 deficiency exacerbated brain ischemia and aggravated RIP2-induced inflammatory response in cerebral ischemic injury." (PMID 38012669, 2023). "In cerebral ischemia, we showed OTUD1 interacted with the kinase domain or CARD domain of RIP2, which facilitated OTUD1 to regulate the ubiquitination of RIP2." (PMID 38012669, 2023). "More importantly, OTUD1 acted as a negative regulator on NF-κB signaling transduction, which directly proved that OTUD1 involved in cerebral ischemia by modulating inflammatory response." (PMID 38012669, 2023). "Altogether, these findings illustrated that OTUD1 ameliorated brain ischemia by interacting with RIP2, which deubiquitinated of RIP2, and consequently repressed RIP2-induced NF-κB signaling pathway and downstream proinflammatory mediators." (PMID 38012669, 2023). "Hence, these data indicated that OTUD1 participated in cerebral ischemia as a negatively regulator of NF-κB activation induced by OGD/R." (PMID 38012669, 2023). "Therefore, OTUD1 was a critical regulator that alleviated brain lesion by repressing RIP2-mediated inflammatory reaction in cerebral ischemia." (PMID 38012669, 2023). "Applying multiple experimental approaches and using both in vitro and in vivo models, our present study showed that protein level of RIP2 and OTUD1 were elevated noticeably in cerebral ischemia induced by MCAO, primary cultured astrocytes and BV2 cells subjected to OGD/R." (PMID 38012669, 2023). "Our results implied a novel ubiquitination regulation mechanism of RIP2 by OTUD1, which in turn could be a potential target for developing novel therapeutical strategy for cerebral ischemia." (PMID 38012669, 2023). "Here, we investigated whether OTUD1 involved in brain ischemia via mediated the deubiquitination of RIP2." (PMID 38012669, 2023). "Given the OTUD1 and RIP2 protein expression were both elevated and localized in microglia and astrocytes of mice with cerebral ischemia, we hypothesize that OTUD1 interacted with RIP2, thus regulate the ubiquitination of RIP2." (PMID 38012669, 2023). "Whether OTUD1 influences the ubiquitination of RIP2 and regulates the inflammatory response in cerebral ischemia remains unclear." (PMID 38012669, 2023). "However, whether OTUD1 regulates the immuno-inflammatory response in cerebral ischemia has not been studied." (PMID 38012669, 2023).
Cognitive impairment (1 paper, 2025). Abnormal cognition is characterized by deficits in thinking, reasoning, or remembering. "The behavioral experiments indicated that OTUD1 knockout could significantly mitigate cognitive impairment in CLP-induced SAE mice." (PMID 40500776, 2025). "In SAE, OTUD1 deubiquitinates HK2, promoting its dissociation from mitochondria, which triggers microglia pyroptosis, leading to neuronal damage and cognitive impairment." (PMID 40500776, 2025).
esophageal cancer (1 paper, 2023). A primary or metastatic malignant neoplasm involving the esophagus. "These researchers identified apoptosis-inducing factor (AIF) as a substrate of OTUD1 in esophageal cancer." (PMID 37153745, 2023).
fungal infections (1 paper, 2023). "OTUD1 regulated the production of antiviral cytokines and inflammatory cytokines by MAVS/TRAF3/TRAF6 signaling or NF-κB signaling cascades during viral and fungal infections." (PMID 38012669, 2023).
Hypervolemia (1 paper, 2025). An increase in the amount of intravascular fluid, particularly in the volume of the circulating blood. "The deubiquitinase OTUD1 appears to be significantly upregulated in hypervolemia." (PMID 41009490, 2025).
osteoporosis (1 paper, 2025). A condition of reduced bone mass, with decreased cortical thickness and a decrease in the number and size of the trabeculae of cancellous bone (but normal chemical composition), resulting in increased fracture incidence. "More notably, the gene expression of OTUD1 was significantly downregulated in the femoral bone tissue of patients with osteoporosis compared to healthy controls." (PMID 40585986, 2025). "OTUD1 represents an ideal upstream target for indirectly enhancing PRDX1 activity in a bone-selective manner for treating osteoporosis and other bone-related diseases." (PMID 40585986, 2025). "Notably, the gene expression of OTUD1 was significantly downregulated in the femoral bone tissue of patients with osteoporosis compared to healthy controls." (PMID 40585986, 2025).
pancreatic ductal adenocarcinoma (1 paper, 2025). An infiltrating adenocarcinoma that arises from the epithelial cells of the pancreas. "In addition, OTUD1 expression was higher in chemoresistant pancreatic ductal adenocarcinoma (PDAC) cells and lower in chemosensitive cells, and silencing of OTUD1 increased the sensitivity of PDAC cells to gemcitabine." (PMID 41050073, 2025).
renal carcinoma (1 paper, 2022). A carcinoma arising from the epithelium of the renal parenchyma or the renal pelvis. "We demonstrated that OTUD1 was downregulated in renal cancer and involved in the poor prognosis of renal cancer." (PMID 35280681, 2022). "In contrast, we showed that OTUD1 depletion decreased the apoptosis of renal cancer cells treated with sunitinib and increased the IC50 values of sunitinib in 786-O and ACHN cells." (PMID 35280681, 2022). "Subsequently, we revealed that downregulation of OTUD1 contributes to the sensitivity of renal cancer cells to TKIs, and this effect was blocked by TNF/NF-kappa B inhibitors and AKT inhibitors." (PMID 35280681, 2022). "Together, these results suggest that OTUD1 contributes to inhibiting renal cancer cell proliferation." (PMID 35280681, 2022). "The CCK-8 assay showed that overexpression of OTUD1 decreased the proliferation of renal cancer cells." (PMID 35280681, 2022). "Collectively, we demonstrated that OTUD1 is downregulated in renal cancer and involved in the poor prognosis of renal cancer." (PMID 35280681, 2022). "It was not surprising that overexpression of inactive mutant of OTUD1 made little effect on the renal cancer cells proliferation compared to the OTUD1 wild type." (PMID 35280681, 2022). "Together, these data suggest that OTUD1 participates in modulating the sensitivity of renal cancer cells to TKIs." (PMID 35280681, 2022). "Next, we investigated whether OTUD1 regulates the sensitivity of renal cancer cells to TKIs through PTEN." (PMID 35280681, 2022). "We then demonstrated that OTUD1 regulates the K48-linked ubiquitination of PTEN, which suggested that OTUD1 might prevent PTEN proteasomal degradation in renal cancer cells." (PMID 35280681, 2022). "Thus, we aimed to study the specific role of OTUD1 in regulating the sensitivity of renal cancer cells to TKIs." (PMID 35280681, 2022). "Then, we studied the biological role of OTUD1 in renal cancer cells." (PMID 35280681, 2022). "Given that OTUD1 functioned as a deubiquitinating enzyme, we would like to investigate whether OTUD1 inhibit the proliferation of renal cancer cells through its deubiquitinating activity." (PMID 35280681, 2022). "Thus, we aimed to study whether the effect of OTUD1 on the sensitivity of renal cancer cells to TKIs is mediated by the AKT and TNF/NF-kappa B signaling pathways." (PMID 35280681, 2022). "OTUD1 was responsible for repressing the PI3K/AKT signaling pathway and NF-kappa B signaling pathway in renal cancer cells." (PMID 35280681, 2022). "Thus, we identified that the OTUD1-PTEN axis suppresses tumor growth and regulates the resistance of renal cancer to TKIs." (PMID 35280681, 2022). "Moreover, analysis of OTUD1 RNA-seq data indicated that OTUD1 inhibition triggers the AKT and NF-kappa B pathways in renal cancer cells." (PMID 35280681, 2022).
renal cell carcinoma (1 paper, 2022). "Consistently, proteomics analysis also indicated that OTUD1 was closely associated with the inhibition NF-kappa B signaling pathway in renal cell carcinoma." (PMID 35280681, 2022).
sarcoidosis (1 paper, 2023). Sarcoidosis is a multisystemic disorder of unknown cause characterized by the formation of immune granulomas in involved organs. "Although the details remain obscure, sarcoidosis is triggered by infection or chemicals, as well as immune responses, and, therefore, the impaired regulation of OTUD1 may be related to sarcoidosis development." (PMID 36829909, 2023).
serous ovarian cancer (1 paper, 2024). "To further support this idea, we analyzed the OTUD1 and ASK1 protein levels and distribution in high- and low-grade serous ovarian cancer tissues, and the results revealed that OTUD1 preferentially aggregated and colocalized with ASK1 in high-grade tissues." (PMID 38351029, 2024). "Among these genes, only OTUD1, a deubiquitinase, was selected because its high level strongly predicts poor prognosis in serous ovarian cancer as well as in several other cancer types." (PMID 38351029, 2024). "OTUD1 is more likely to be overexpressed in high-grade serous ovarian cancer tissues, and its overexpression is sufficient for aggresome-like organelle formation via its N-terminal intrinsically disordered region." (PMID 38351029, 2024).